HERC3 (HECT and RLD domain containing E3 ubiquitin protein ligase 3)
Description:
E3 ubiquitin-protein ligase which accepts ubiquitin from an E2 ubiquitin-conjugating enzyme in the form of a thioester and then directly transfers the ubiquitin to targeted substrates.
Synonyms: KIAA0032
Tractability: PROTAC: UniProt records ubiquitination sites on it; ubiquitination databases record sites on it.
Gene: Protein-coding gene on chromosome 4 (88,592,434 to 88,708,540, forward strand). Ensembl gene ENSG00000138641.
Subcellular location: Cytoplasm; Cytoplasmic vesicle
Subcellular location (Human Protein Atlas): Cytosol
Pathways (Reactome):
Immune System: Antigen processing: Ubiquitination & Proteasome degradation
Gene Ontology:
Molecular function: protein binding; ubiquitin protein ligase activity; ubiquitin-protein transferase activity
Biological process: protein ubiquitination; ubiquitin-dependent protein catabolic process
Cellular component: cytosol; cytoplasm; cytoplasmic vesicle
Genetic constraint (gnomAD): Loss-of-function variants: 26 observed, 82.21 expected, observed/expected ratio (o/e) 0.32, 90% interval 0.23 to 0.44. The upper end of that interval is the gene's LOEUF score, 0.44, which puts it in group 1 of 6, group 1 being the genes least tolerant of losing a copy. Missense variants: 615 observed, 990.63 expected, observed/expected ratio (o/e) 0.62, 90% interval 0.58 to 0.66. Synonymous variants: 336 observed, 375.4 expected, observed/expected ratio (o/e) 0.9, 90% interval 0.82 to 0.98.
Homologues: Orthologues: chimpanzee HERC3 (100% identical), macaque HERC3 (99% identical), dog HERC3 (99% identical), rabbit HERC3 (98% identical), guinea pig HERC3 (98% identical), pig HERC3 (98% identical), rat Herc3 (96% identical), mouse Herc3 (95% identical), tropical clawed frog herc3 (78% identical), zebrafish herc3 (66% identical). Paralogues in human: HERC4 (56% identical), HERC6 (37% identical), HERC5 (33% identical), HERC2 (28% identical), UBE3A (21% identical), HECTD4 (19% identical), HECTD2 (18% identical), HECW1 (18% identical), HECW2 (18% identical), HECTD1 (17% identical), TRIP12 (16% identical), ITCH (16% identical), and 12 more.
Diseases named in the same sentence as HERC3 in open-access papers:
HERC3 is named in the same sentence as 13 diseases in open-access papers, as found by Europe PMC text mining. Sharing a sentence is not in itself a finding about the gene and the disease. The quoted sentences say what the papers report.
glioblastoma (5 papers, 2021 to 2022). The most malignant astrocytic tumor (WHO grade IV). "For instance, HERC3 was reported to be a tumor suppressor via regulating SMAD7 in glioblastoma." (PMID 34195188, 2021). "And to our knowledge, HERC3 is only once reported to promote ubiquitination degradation SMAD7 and induces autophagy-mediated EMT in glioblastoma." (PMID 35064108, 2022). "For example, HERC3 was reported to mediate the ubiquitination and the degradation of SMAD7 in glioblastoma." (PMID 34195188, 2021). "Relevant research on HERC3 in terms of cancers is rare, and HERC3 was once reported to affect SMAD7 ubiquitination degradation and induce the autophagy–mediated epithelial–mesenchymal transition (EMT) and chemoresistance in glioblastomas." (PMID 35889210, 2022). "The relevant research of HERC3 in terms of cancers is rare, HERC3 is once reported to mediate SMAD7 ubiquitination degradation and induce the autophagy-mediated EMT and chemoresistance in glioblastoma." (PMID 35064108, 2022). "Moreover, ectopic HERC3 expression was correlated with TMZ resistance in glioblastoma (GBM) cells." (PMID 33935743, 2021).
colorectal cancer (3 papers, 2022). A primary or metastatic malignant neoplasm that affects the colon or rectum. "Taken with the clinical information together, interestingly, HERC3 was enriched once again indicating its crucial role in colorectal cancer." (PMID 35637966, 2022). "Through bioinformatics analysis and experimental confirmation, HERC3 was demonstrated to be downregulated in colorectal cancer tissues and also to be negatively correlated with SOX18 in osteosarcomas." (PMID 35889210, 2022). "A recent study demonstrated that HERC3 could directly interact with EIF5A2 and promote the K27– and K48–linked ubiquitination degradation of EIF5A2 to regulate EMT in colorectal cancers." (PMID 35889210, 2022).
breast carcinoma (2 papers, 2022 to 2023). "Simultaneously, our current findings indicate a tumor suppressor role for HERC3 in breast cancer development." (PMID 35889210, 2022). "In this study, a new ERK2 degrader, Z734, was found to suppress breast cancer growth by inducing cell apoptosis, and a tumor suppressor role of HERC3 in breast cancer development was revealed." (PMID 35889210, 2022). "In addition, it has been reported that HERC3 has ubiquitin ligase activity and is involved in the tumorigenesis of breast carcinoma." (PMID 35889210, 2022). "HERC1 is the founding member of the HERC family characterized in human breast cancer cells, followed by the identification of a total of six HERC members in human, which are phylogenetically divided into large HERCs (HERC1 and HERC2) and small HERCs (HERC3-6)." (PMID 36902023, 2023).
co-infection (1 paper, 2022). "After co-infection, several cell proliferation-related assays including EdU assays, CCK-8, and colony formation were performed, and the results indicated that upregulated RPL23A could attenuate the effects on CRC cell proliferation induced by HERC3 overexpression and vice versa." (PMID 35637966, 2022).
diabetes (1 paper, 2024). "Also, applying models of diabetes and retinal injury to Herc3 deficient mice may shine some light on the potential impact of this specific E3 ubiquitin ligase in retinal diseases in which the ubiquitin proteasome system is thought to play an important role." (PMID 38321224, 2024).
retinal degeneration (1 paper, 2024). Degeneration of the retina. "This association between Herc3 deficiency, retinal microglial activation and retinal degeneration merits further study." (PMID 38321224, 2024). "Combining all of these pieces of information, we feel confident that the retinal degeneration and fundus spot accumulation we are observing are indeed secondary to the Herc3 mutation." (PMID 38321224, 2024). "While it is possible that Herc3 deficiency could also be directly responsible for the microglial activation, similar activation of retinal microglia is seen in other models of retinal degeneration." (PMID 38321224, 2024). "It is likely that, while the fundus spots helped us identify Herc3 as an essential gene for retinal health, the retinal degeneration may be the most important and perhaps primary effect of the deficiency of Herc3." (PMID 38321224, 2024). "Next, we generated Herc3-/- mice using CRISPR-mediated gene editing and corroborated that they developed a prominent accumulation of activated subretinal microglia, retinal degeneration, and a decrease in retinal function." (PMID 38321224, 2024).
Stroke (1 paper, 2021). Sudden impairment of blood flow to a part of the brain due to occlusion or rupture of an artery to the brain. "In addition, circ_Dlgap3_1, circ_Tasp1_7, circ_Herc3_2, and circ_Chd2_24 targeted the antiapoptotic protein, Bcl-2, as well as apoptotic protease activating factor 1, supporting their participation in the apoptotic process after stroke." (PMID 34868302, 2021).
tumor (10 papers, 2018 to 2024). "Here, we discovered for the first time that HERC3 was associated with the tumor size, suppressed CRC cell growth and blocked the cell cycle at the G0-G1 phase." (PMID 35637966, 2022). "Interestingly, in the present study, HERC3 was firstly found to be associated with tumor size and Ki67 staining, an index for evaluating proliferative capacity of cancer cells." (PMID 35637966, 2022). "Interestingly, we here discovered that HERC3 protein expression was associated with tumor size and Ki67 staining, an index for evaluating proliferative capacity of cancer cells, indicating that HERC3 might also affect CRC cell proliferation." (PMID 35637966, 2022). "They discovered that the expression of HERC3 was significantly downregulated in CRC tumor tissues and cell lines, and the downregulated HERC3 was closely related to shorter overall survival and disease-free survival in CRC patients." (PMID 36831013, 2023). "The mRNA expression of HERC3 was downregulated in 70 CRC tumor tissues compared with the paired adjacent-normal tissues." (PMID 35064108, 2022). "We randomly selected 8 paired CRC tumor and adjacent-normal tissues to detect the protein expression of HERC3 through western blotting." (PMID 35064108, 2022). "Based on patient samples, it was further confirmed that the protein expression levels of HERC3 in CRC tissue was lower than in tumor-adjacent samples." (PMID 35637966, 2022). "When combing colon epithelial tissues from GTEx and CRC normal tissues from TCGA together, the expression of HERC3 decreased a lot in CRC tumor tissues from TCGA compared with the former merged one." (PMID 35064108, 2022). "They explained that small HECT and RCC1-like domain (HERC3) was found to be highly expressed in pseudopalisade cells around a tumor’s adjacent tissues and in tumor necrosis." (PMID 33525678, 2021). "Interestingly, we also found that the expression of HERC3 gradually decreased from normal colonic epithelial tissues to CRC patient adjacent-normal tissues to CRC patient tumor tissues." (PMID 35064108, 2022). "However, some patients also showed high expression of HERC3 in tumor tissues compared to tumor-adjacent tissues." (PMID 35064108, 2022). "Based on the gradient differential expression trend of HERC3 from normal colorectal epithelial tissues to tumor-adjacent-normal tissues and to CRC tissues, HERC3 may play an important role in the whole process of CRC development." (PMID 35064108, 2022). "It was found that HERC3 regulated autophagy in tumor cells via downregulating SMAD7 expression." (PMID 33525678, 2021). "Collectively, these results indicate that HERC3 may be a potential tumor suppressor in CRC." (PMID 36831013, 2023). "Moreover, the protein expression of HERC3 was downregulated in CRC tumor tissues." (PMID 35064108, 2022). "Thus, HERC3 could serve as a rigorous tumor suppressor through RPL23A/c-Myc/p21 axis." (PMID 35637966, 2022). "Interestingly, HERC3 showed a gradual decrease trend from healthy individual’s colonic epithelial tissues to CRC patients’ tumor-adjacent-normal tissues to CRC patients’ tumor tissues that implied that HERC3 might involve in the whole process of CRC including initiation and progression." (PMID 35064108, 2022). "In this study, we identified that HERC3 was gradually reduced from colorectal tissues in healthy individuals to adjacent-tumors normal tissue in CRC patients, and to tumor tissues." (PMID 35637966, 2022). "Extensive search of the literature revealed a potential key role of genes at the identified porcine loci in tumor invasion (DST, PLEKHA5, CBY1, LIMK2 and ETV5) and immune response modulation (ETV5, HERC3 and DICER1) of the progression phenotypes." (PMID 29963229, 2018). "Besides, 50 CRC tumor tissues were used to research the correlation between RPL23A and HERC3 through IHC, and the results indicated that there was a negative correlation between HERC3 and RPL23A." (PMID 35637966, 2022).
tumor (continued). "Interestingly, expression levels of HERC3, KCNN2, and MRPL52 were not significantly varied in tumor group and control group." (PMID 38918720, 2024).
cancer (3 papers, 2022). A tumor composed of atypical neoplastic, often pleomorphic cells that invade other tissues. "HERC3 was correlated with T, N, and M stage which was associated with the cancer cell invasion, migration and metastasis, further experiments were performed." (PMID 35064108, 2022). "In addition, HERC3 was indicated to be associated with T, N, and M stage which was associated with the cancer cell migration, invasion, and metastasis, further experiments were performed." (PMID 35064108, 2022). "However, studies focusing on the functions of HERC3 in cancer is still rare." (PMID 35064108, 2022).
HERC3 also shares sentences with these, for which no sentence is quoted: atherosclerosis (1 paper); autoimmune disease (1); metastatic tumor (1); retinal diseases (1).